SMARCE1 (SWI/SNF related BAF chromatin remodeling complex subunit E1)
Diseases named in the same sentence as SMARCE1 in open-access papers (continued):
Sharing a sentence is not in itself a finding about the gene and the disease.
tumor (25 papers, 2013 to 2025). "To confirm that tumor-associated proteases are decreased at the protein level upon SMARCE1 knockdown, we simultaneously measured expression of 35 proteases in a single sample using multiplexed western blots." (PMID 38437557, 2024). "Immunohistochemical detection of SMARCE1 showed widespread nuclear loss of expression in the tumor cells in all analyzed cases (n = 25)." (PMID 33319313, 2021). "Tumors from individuals with SMARCE1 mutations were of clear-cell histological subtype, and all had loss of SMARCE1 protein, consistent with a tumor suppressor mechanism of this gene." (PMID 30279357, 2018). "Tumor DNA showed loss of heterozygosity (LOH) of the wild-type allele or a second inactivating mutation as a second hit in some tumors, implying a tumor suppressor function of the SMARCE1 gene." (PMID 26803492, 2016). "Together, these observations suggest that higher expression of SMARCE1 and PTK2 increases risk of tumor relapse, and SMARCE1 likely plays a key role in regulating PTK2 expression in luminal B and basal-like tumors." (PMID 27495308, 2016). "This will help to better estimate the age- and gender-dependant penetrance of the disease and gain more certainty about the complete tumor spectrum for carriers of a SMARCE1 mutation." (PMID 26803492, 2016). "Immunohistochemistry revealed nuclear loss of SMARCE1 expression in the tumor cells." (PMID 38321548, 2024). "However, it is noteworthy that immunohistochemically, nuclear loss of the SMARCE1 expression in the tumor cells was confirmed in our case." (PMID 38321548, 2024). "Targeted DNA sequencing revealed SMARCE1 mutations in 33/34 analyzed samples, accompanied by a nuclear loss of expression determined via immunohistochemistry and a decreased SMARCE1 transcript expression in the tumor cells." (PMID 33319313, 2021). "The 11 coupregulated factors included PTPRC (a positive regulator of T-cell activation), IFI16 (a hematopoietic differentiation modulator), and SMARCE1 (a chromatin remodeler that enhances tumor suppressor accessibility)." (PMID 41304891, 2025). "We report the concentric self-assembly of LbL NPs that encapsulate a high weight percentage of SMARCE1 siRNA and include an external layer of tumor targeting and synthetic biosensing peptides." (PMID 38437557, 2024). "Three weeks after injection, lung tumor burden was ∼10-fold lower in mice injected with SMARCE1-inhibited cancer cells on the DOX diet compared with mice injected with cells on the standard diet." (PMID 38437557, 2024). "We then i.p. administered the siSE-LbL and siNT-LbL NPs to the orthotopic tumor-bearing animals and observed 67% knockdown in SMARCE1 mRNA levels after four sequential injections, one dose per week." (PMID 38437557, 2024). "Nuclear expression of SMARCE1 was found in tumor cells, non‐neoplastic and metaplastic epithelium, and most prominently and consistently in lymphocytes, which served as an internal positive control." (PMID 36916408, 2023). "Most strikingly, we found heterozygous loss of two tumor suppressor genes, ARID1A and SMARCE1, components of the chromatin remodeling complex SWI/SNF, and one copy gain of SUZ12 and EZH1, the components of another essential chromatin remodeling complex PRC2." (PMID 32724039, 2020). "For example, resistance to rituximab and doxorubicin was conferred by CRISPRi of SMARCE1, a known tumor suppressor in DLBCL and other cancers, and by CRISPRi of CAD, a protein involved in pyrimidine biosynthesis whose knockdown causes S phase arrest." (PMID 31742555, 2019). "To identify the steps of the metastatic cascade that requires SMARCE1 activity, we examined the effect of SMARCE1 knockdown on the ability of tumor cells to survive circulation and colonize lungs by using an experimental metastasis model." (PMID 27495308, 2016). "Together, these results suggest that SMARCE1 knockdown diminish the ability of tumor cells to survive circulation." (PMID 27495308, 2016).
tumor (continued). "To examine the effect of SMARCE1 knockdown on the migratory and invasive potential of tumor cells, we performed Boyden chamber transwell assays." (PMID 27495308, 2016). "The evidence of the few cases of SMARCE1-related CCMs that have been published so far, together with the evidence of the patient reported here, shows that the SMARCE1 gene also acts as a tumor suppressor gene." (PMID 26803492, 2016). "By examining the number of tumor cells in blood, we found that SMARCE1 knockdown significantly reduced the number of circulating tumor cells (p = 0.0011)." (PMID 27495308, 2016). "Together, these results suggest that SMARCE1 activity is dispensable for primary tumor outgrowth, but essential for distant metastasis of MDA-MB-231 cells." (PMID 27495308, 2016). "Additionally, the synthetic biomarkers are released after cleavage by proteases downstream of SMARCE1 in the tumor microenvironment." (PMID 38437557, 2024). "After confirming that knockdown of SMARCE-1 results in decreased tumor burden, we sought to determine the protease activity landscape following knockdown, to evaluate whether protease sensing could be leveraged as a readout." (PMID 38437557, 2024). "We detected significantly decreased urinary reporter concentration in the urine of tumor-bearing mice treated with siSE-LbL NPs relative to mice that received siNT-LbL NPs, signaling that the observed SMARCE1 knockdown was paralleled by decreased MMP protease activity." (PMID 38437557, 2024). "After accumulation at the tumor site, siRNA is delivered intracellularly to knockdown SMARCE1." (PMID 38437557, 2024). "TrxG proteins SMARCD1 and SMARCE1 have been reported to promote tumor progression." (PMID 37581938, 2023). "Furthermore and unlike the other tested subunits of the SWI/SNF complex, SMARCA4 and SMARCE1 were homogeneously affected, that is, discovered in every tumor sample of a primary tumor each in two cases, respectively." (PMID 36916408, 2023). "There is also evidence that SMARCE1 has a tumor suppressor function." (PMID 34788294, 2021). "Mechanistically, TAK-981 de-SUMOylates the cBAF subunit SMARCE1, stabilizing and restoring cBAF on chromatin, shifting away from SS18::SSX-ncBAF-driven transcription, associated with DNA damage and cell death and resulting in tumor inhibition across both human and mouse SS tumor models." (PMID 38883782, 2024). "Similarly, we observed an enrichment of SMARCE1 and SMARCB1, two proteins that are core components of the BAF (SWI/SNF) chromatin remodeling complex and have been implicated as inhibitors of tumor formation." (PMID 30046396, 2018). "Most of the examined cases showed a diffusely distributed expression pattern of different staining intensities within the same tumor for both SMARCA4 and SMARCE1." (PMID 36916408, 2023). "Total RNA was extracted from tumor nodules in animals on chow diet with (SMARCE1 knockdown) or without DOX (SMARCE1-expressing)." (PMID 38437557, 2024). "This study of an independent White GC cohort aimed to examine the potential tumor biological significance regarding the expression of SMARCA4 and SMARCE1 along with the expression patterns and correlation with other important genetic characteristics like MSI and EBV status." (PMID 36916408, 2023). "So far, no other tumor types than spinal and intracranial CCMs have been described in SMARCE1-positive patients." (PMID 26803492, 2016). "Again, the protein was lost in the tumor samples but not in normal tissue, thus suggesting a classic Kundson biallelic inactivation and a tumor suppressor role of SMARCE1." (PMID 25676695, 2015). "Although SMARCE1 plays an essential role for the escape of tumor cells from the normal tissue architecture into the surrounding matrix, the potential of SMARCE1 inhibition to prevent tumor progression has yet to be explored due to the lack of drugs targeting transcription factors." (PMID 38437557, 2024).
cancer (21 papers, 2012 to 2025). A tumor composed of atypical neoplastic, often pleomorphic cells that invade other tissues. "For example, SMARCE1 is a core subunit of the SWI/SNF chromatin remodeling complex that has been linked to invasiveness in a hormone-independent manner in additional cancers." (PMID 33413550, 2021). "To gain insights into the molecular mechanisms underlying SMARCE1-mediated anoikis resistance, we sought to identify signaling pathways regulated by SMARCE1 in detached cells by using chemical inhibitors of several signaling pathways that have been linked to anoikis resistance of cancer cells." (PMID 27495308, 2016). "We engineered the invasive OVCAR8 cancer cell line with silenced SMARCE1 (OVCAR8-shSMARCE1) by stably expressing shRNA to inhibit SMARCE1 expression." (PMID 38437557, 2024). "Two of the cancer gene products in the proximity proteome are known to physically interact with the N-CoR complex (SMARCE1 and SPEN)—suggesting these may all operate through a similar mechanism." (PMID 39767807, 2024). "Similarly, terms associated with estrogen signaling, cancer progression, MYC, and SMARCE1-dependent targets were oppositely regulated." (PMID 37082578, 2023). "However, other subunits such as SMARCE1 (BAF57), SMARCA2 (BRM) and SMARCAD1 (BAF60a) were implicated to promote cancers." (PMID 33670012, 2021). "It is indicated that the effect of SMARCE1 (BAF57) on regulating cyclin D1 splicing may also contribute to cancer progression." (PMID 33670012, 2021). "Notably, two trunk genes (SPEN and ITK), a branch gene (SMARCE1), and several private genes (FAT4, CACNA1D, ATR, RUNX1T1, TERT, and SRGAP3) were defined as cancer-associated genes, according to the cancer gene census." (PMID 28716121, 2017). "Also, some of the recently discovered cancer predisposing genes appear to act in accordance with this scenario, such as for instance the MAX, SMARCE1 and BAP1 genes." (PMID 27279102, 2016). "However, we have noticed upon interrogation of the Broad Institute depository (Depmap) that RNF4 silencing is more toxic to SS than it is to 30 other cancer subtypes, confirming our hypothesis that increased SMARCE1 expression is the linchpin of the exquisite toxicity of TAK-981 in SS." (PMID 41193430, 2025). "On chromosome 17q12‐21, SMARCE1 is located closely to ERBB2 and both genes can be co‐amplified in cancer." (PMID 36916408, 2023). "The other genes (SMARCE1, DISC1, CENTD2, RHOT1, ARHGAP6, ARHGEF9 and ARHGEF11) are also involved in cancer progression or chemoresistance." (PMID 23300757, 2012). "SMARCE1 and HN1 have been reported to regulate the metastatic potential of cancer cells." (PMID 34001881, 2021).
genetic disorder (1 paper, 2020). "This genetic disorder is caused by de novo mutations of ARID1A (CSS2; 1p36.11; MIM 614607), ARID1B (CSS1; 6q25.3; MIM 135900), DPF2 (CSS7; 11q13.1; MIM 618027), SMARCA4 (CSS4; 19p13.2; MIM 614609), SMARCB1 (CSS3; 22q11.23; MIM 614608) or SMARCE1 (CSS5; 17q21.2; MIM 616938) genes." (PMID 32916978, 2020).
infection (1 paper, 2011). The state of being infected such as from the introduction of a foreign agent such as serum, vaccine, antigenic substance or organism. "The down-regulated miR-29b and miR-29a are both or each connected to up-regulated SMARCE1, HBO1, NKX6-1, HOXA10, HBP1, OTUD4, that could be further considered as potent targets during infection." (PMID 21408164, 2011).
SMARCE1 also shares sentences with these, for which no sentence is quoted: asthma (2 papers); developmental delay (2); glioma (2); melanoma (2); Secretory Meningioma (2); tumor predisposition syndrome (2); adult onset asthma (1); allergic disease (1); Cerebellar atrophy (1); cervical cancer (1); childhood cancer (1); CHOPS syndrome (1); Cowden syndrome (1); endometrial cancer (1); esophageal cancer (1); familial meningioma (1); fragile X syndrome (1); hereditary cancer (1); hypertrichosis (1); infantile hemangiomas (1); intracranial meningioma (1); KBG syndrome (1); keratoconus (1); kidney malformations (1); neuroblastoma (1); neurodevelopmental disorder (1); neurofibromatosis type 2 (1); neurological disorders (1); nevoid basal cell carcinoma syndrome (1); Nicolaides-Baraitser syndrome (1).
A further 14 diseases each share a sentence with SMARCE1 in 1 paper.